FOXK1 (forkhead box K1)
Diseases named in the same sentence as FOXK1 in open-access papers (continued):
Sharing a sentence is not in itself a finding about the gene and the disease.
cancer (38 papers, 2016 to 2025). A tumor composed of atypical neoplastic, often pleomorphic cells that invade other tissues. "Because c-jun has previously been implicated in cancer cell growth and metastasis, we investigated whether c-jun and FOXK1 expression are correlated in GC." (PMID 27882939, 2016). "Especially, oncogenic activity of FOXK1was remarkably decreased as a consequence of inhibited motility and invasiveness of cancer cells suggesting its important participation in CRC progression characterized by high expression of FOXK1." (PMID 40032945, 2025). "The involvement of FOXK1 in activating the AKT/mTOR signaling pathway further supports its implication in the malignancy of various cancers." (PMID 39981141, 2025). "FOXM1 and FOXK1 have critical oncogenic roles in cancer through their antagonism of apoptotic signals and their promotion of cell proliferation, metastasis, angiogenesis, and therapeutic resistance." (PMID 37174744, 2023). "Characterization of FOXK1 has identified its functions in multiple cancer hallmarks, including proliferation, metastasis, angiogenesis, and apoptosis, as well as its roles in metabolism." (PMID 37174744, 2023). "For instance, FOXK1, a specific TF of immortal cancer cells, plays a key role in regulating cell viability, proliferation, and life span." (PMID 37853464, 2023). "FOXK1 upregulation in HCC cells led to expand the population of cancer stem cells by increasing EpCAM and ALDH1 expression levels." (PMID 35255005, 2022). "FoxK1/2 is an essential transcription factor that regulates cell proliferation, survival, skeletal muscle regeneration, myogenic differentiation, and cancer development." (PMID 35903069, 2022). "SNHG1 knockdown delayed cancer progression both in vitro and in vivo by upregulating miR-376a and downregulating FOXK1 and Snail." (PMID 34095464, 2021). "FOXK1, a transcript well known for functions related to extensive cancer progression activity, drew our attention." (PMID 32138762, 2020). "The level of FOXK1 expression in normal tissues adjacent to cancer tissues was significantly lower than that in the cancer tissues." (PMID 32268297, 2020). "The role and function of FOXK1 in cancer have been widely studied, but the metastasis of tumors under acidic conditions is not well understood." (PMID 32268297, 2020). "Currently, growing evidence has indicated FOXK1 is overexpressed in various cancer tissues and functions as a oncogene." (PMID 32363163, 2020). "Two of these 35 mRNAs, PDLIM7 and FOXK1, showing a significant and positive association with both, IGF2BP1 and SRF expression in cancer, as indicated for HCC and EOC, were chosen for validating regulation by IGF2BP1 and SRF." (PMID 30371874, 2019). "In this study, we used ovarian tissue samples to explore FOXK1 expression profiles in adjacent normal tissues and cancer tissues." (PMID 29050292, 2017). "Recently, there were several researches revealed that FOXK1 facilitated proliferation, invasion and metastasis in different cancer." (PMID 29050292, 2017). "To validate our findings in vivo, we investigated the correlation between RUFY3 and FOXK1 expression in 91 pairs of adjacent normal colon mucosal tissues and cancer tissues." (PMID 28623323, 2017). "RUFY3 and FOXK1 were expressed at high and intermediate levels, respectively, in the cytoplasm and nucleus of cancer cells." (PMID 28623323, 2017). "In the GENT database, FOXK1 is upregulated in cancers of the adrenal gland, head neck, kidney, liver, lung, pancreas, skin, vulva and colon compared with corresponding normal tissues." (PMID 27892920, 2016). "To validate our findings in vivo, we investigated the correlation between c-jun and FOXK1 expression in 90 pairs of adjacent normal gastric mucosal tissues and cancer tissues." (PMID 27882939, 2016). "We found that FOXK1 was overexpressed in cancer tissues and further identified, for the first time, the role of FOXK1 in promoting EMT." (PMID 27882939, 2016).
cancer (continued). "In this study, we showed that FOXK1 expression is elevated in cancer tissues and that FOXK1 overexpression promotes the proliferation, migration and invasion of GCs." (PMID 27882939, 2016). "FOXK1 overexpression progressed from a pronounced increase in vector cells at day 15 to a 4.4-fold increase in cancer area 30 days after injection." (PMID 27892920, 2016). "We detected FOXK1 and c-jun expression in regional lymph node metastatic GC tissue and found that FOXK1 and c-jun were expressed at high levels in the nucleus of cancer cells." (PMID 27882939, 2016). "To assess the influence of FOXK1 on cancer cell migration and invasion, we first examined FOXK1 expression in primary CRC tissues by IHC." (PMID 27223064, 2016). "In this study, we report on FOXK1, a gene that is over-expressed in various cancers, including CRC, acts as an important oncogene." (PMID 27223064, 2016). "Our study used tissue arrays to investigate FOXK1 expression profiles in various normal and cancer tissues." (PMID 27223064, 2016). "Here, we found that FOXK1 protein expression was higher in 8/10 (80.0%) fresh cancer tissues compared with that in adjacent normal tissues." (PMID 27882939, 2016). "Further investigation into other human cancers may reveal whether FOXK1 has prognostic value in a broader range of human cancers than is currently understood." (PMID 37174744, 2023). "FoxK1 protein expression is higher in 80% of fresh cancer tissues than in adjacent normal tissues." (PMID 35903069, 2022). "Furthermore, the role of foxK1 in controlling apoptosis deserves further attention, since a functional relationship between FoxK and apoptosis has only been suggested in cancer cells." (PMID 35273960, 2022). "Additionally, the Forkhead box (FOX) family of transcription factors (FOXF1, FOXS1, FOXM1, FOXK1, FOXP4, and FOXC1) play a role in cell differentiation and proliferation and are implicated in cancer and drug resistance." (PMID 35854219, 2022). "FoxK1/2 regulates the expression of a series of downstream target genes as a transcription factor, thereby affecting multiple signaling pathways and biological behaviors of cancer cells." (PMID 35903069, 2022). "Previous studies have identified a crucial role of FOXK1 in cancers." (PMID 32138762, 2020). "We found that the expression of FOXK1 was correlated with metastasis, so we hypothesized that FOXK1 incresed cancer cell metastasis." (PMID 29050292, 2017). "Strong FOXK1-positive signals were present in the cancer cell nuclei." (PMID 27882939, 2016). "Because FHL2 has been previously implicated in cancer cell growth and metastasis, we investigated whether a correlation exists between FHL2 and FOXK1 expression in CRC." (PMID 27892920, 2016). "Moreover, miR-646 inhibits cancer development by downregulating oncogenes, such as FOXK1 and EGFR." (PMID 39519267, 2024). "Among them, we selected FOXK1 transcription factor, which belongs to the Forkhead family of the winged-helix DNA binding domain because it is expressed in migratory NC cells of Xenopus embryos and has been shown to promote invasion and metastasis of various cancer types." (PMID 32214200, 2020). "Interestingly, since both YBX1 and FOXK1 served as transcription factors in the nuclei of cancer cells, overexpression of lncRNA HUMT might lead to a chain reaction that could amplify the functions of upstream signals." (PMID 32138762, 2020). "Other regulators such as FOXK1, MUC1, PGC-1α, SRC are reported to be involved in miR-485-5p-mediated inhibition of cancer cell proliferation, migration and invasion." (PMID 35706019, 2022). "Dysregulation of several of our candidates (BMP2K, CBLL1, DAB2, MCRS1, FOXK1, PEG10 and YEATS2) has previously been reported to contribute to different types of cancer." (PMID 34689785, 2021).
cancer (continued). "Recently, an increasing studies have reported that the Forkhead transcription factor family members including FOXK1 induce EMT and aggressiveness in human cancer." (PMID 32363163, 2020). "Patients with high FOXK1 expression in the TCGA-TNBC cohort also showed a higher level of TGF-β, which was considered as an immunosuppressive factor in cancer." (PMID 32138762, 2020). "Taken together, our findings indicated that lncRNA HUMT promotes cancer cell proliferation, lymph node metastasis, and lymphangiogenesis by HUMT/YBX1/FOXK1-mediated Akt/mTOR and VEGFC signaling." (PMID 32138762, 2020). "If the SRF/IGF2BP1-dependent enhancement of FOXK1 and PDLIM7 has prognostic value in cancer, it was evaluated by Kaplan–Meier analyses using KM plotter." (PMID 30371874, 2019). "The majority of these SRF/IGF2BP1-enhanced genes, including PDLIM7 and FOXK1, show conserved upregulation with SRF and IGF2BP1 synthesis in cancer." (PMID 30371874, 2019). "This regulation was associated with a substantial recovery of spheroid growth upon SRF depletion suggesting that FOXK1 and PDLIM7 are part of a SRF/IGF2BP1-dependent ‘effector network’ in cancer cells." (PMID 30371874, 2019). "Conversely, FOXK1 knockdown in RUFY3-overexpressing cells led to weak and aggregated F-actin filaments that are involved in cancer cell invasion and metastasis." (PMID 28623323, 2017). "FOXK1 located mainly in the nucleus, and FHL2 disseminated at both the nucleus and cytoplasm of the same cancer cells." (PMID 27892920, 2016). "Previous studies indicated that BAP1 might inhibit cancer cell growth by interacting with one or more partner proteins, including YY1, RBBP7, HCF-1, H2A, ASXL1/2, and FoxK1/K2." (PMID 40688406, 2025). "FOXK1, like MYC, regulates several biological processes related to cancer initiation, development, metastasis, angiogenesis, and drug resistance, explaining the importance of deregulated FOXK1 in various types of cancers." (PMID 34689785, 2021). "Both transcripts (FOXK1 and PDLIM7) were decreased upon the knockdown of IGF2BP1 suggesting a substantial conservation of SRF/IGF2BP1-dependent regulation of both factors in cancer cells." (PMID 30371874, 2019). "We observed that FOXK1 and FHL2 had higher expression in cancer samples." (PMID 27892920, 2016). "The majority (8/10) of cancer tissues (C) exhibited higher FOXK1 expression level compared with the corresponding non-cancerous controls (N)." (PMID 27882939, 2016). "The majority (9/10 or 90%) of cancer tissues (T) exhibited a higher expression level of FOXK1 relative to their corresponding non-cancerous controls." (PMID 27892920, 2016). "Due to protein-RNA interactions, ZRANB2 stabilizes the SNHG20 lncRNA, promotes the degradation of Forkhead box K1 (FOXK1), and increases the transcription of MMP-1, MMP-9, and VE-cadherin; this stimulates proliferation, migration, invasion, and VM development in this type of cancer." (PMID 31993365, 2019).
metabolic disease (1 paper, 2022). A congenital disorder (due to inherited enzyme abnormality) or acquired (due to failure of a metabolically important organ) disorder resulting from an abnormal metabolic process. "In addition, the role of FoxK1/2 in non-neoplastic diseases, such as cardiovascular diseases and metabolic diseases, also deserves attention." (PMID 35903069, 2022).
FOXK1 also shares sentences with these, for which no sentence is quoted: bladder cancer (2 papers); hematological malignancies (2); lung adenocarcinoma (2); alcoholism (1); breast (1); cervical cancer (1); chronic kidney disease (1); esophageal squamous cell carcinoma (1); glioblastoma (1); infection (1); intrahepatic cholangiocarcinoma (1); liver disease (1); meningioma (1); metastatic melanoma (1); myxoma (1); nonalcoholic fatty liver disease (1); periodontitis (1); prostate carcinoma (1); pulmonary fibrosis (1); renal cell carcinoma (1); rheumatoid arthritis (1).